STN1 (STN1 subunit of CST complex)
Diseases named in the same sentence as STN1 in open-access papers:
STN1 is named in the same sentence as 59 diseases in open-access papers, as found by Europe PMC text mining. Sharing a sentence is not in itself a finding about the gene and the disease. The quoted sentences say what the papers report.
melanoma (13 papers, 2014 to 2025). A malignant, usually aggressive tumor composed of atypical, neoplastic melanocytes. "Previous GWAS studies reported that STN1 (aka OBFC1) deregulation is associated with melanoma, implicating a potential role of STN1 or CST in skin tumorigenesis." (PMID 40501869, 2025). "In contrast, among the total of 29 STN1-deficient animals (13 males and 16 females), only two male mice and one female animal developed melanoma at 3–5 months of UV exposure." (PMID 40501869, 2025). "Interestingly, our results showed some gender-specific differences in melanoma development, with male STN1-deficient mice showing a slight increase in melanoma formation." (PMID 40501869, 2025). "Thus, we were unable to make a definitive conclusion about the effect of gender difference in melanoma formation in STN1 deficient animals." (PMID 40501869, 2025). "Interestingly, the STN1-deficient male cohort showed a moderate increase in melanoma formation and the female STN1-deficient mice showed a reduction in melanoma formation." (PMID 41237160, 2025). "Previous GWAS studies have found that STN1 deregulation is associated with melanoma." (PMID 40501869, 2025). "However, statistical analysis showed no significance of tumor incidences in male (p = 0.539, two-sided Fisher exact tests) or female (p = 0.206, two-sided Fisher exact tests) cohort between STN1-deficient mice and control animals, probably due to the lower number of melanoma-positive animals." (PMID 41237160, 2025). "In addition, STN1 downregulation and/or mutations have been reported in a number of cancers, including colorectal cancer, epithelial ovarian cancer, leukemia, thyroid cancer, melanoma, and uterine cancer (and references therein)." (PMID 40497960, 2025). "Our data show that STN1 depletion in mature melanocytes produces a marginal decrease in melanoma incidence in female mice but a slight increase in males, although the differences are statistically insignificant." (PMID 41237160, 2025). "Our result shows that the overall melanoma incidence in STN1-deficient mice is no different from the control littermates (p=1.000, two-sided Fisher exact tests)." (PMID 40501869, 2025). "The majority of STN1-deficient mice did not develop visible melanoma even after prolonged UV exposure for 10 months and survived prolonged UV exposure." (PMID 40501869, 2025). "This study provides the first in vivo evidence that STN1 deficiency in melanocytes does not significantly impact UV-induced melanoma development in adult mice, despite in silico associations between CST dysfunction and melanoma." (PMID 40501869, 2025). "Additionally, the UV exposure protocol used in this study, while sufficient to induce melanoma in the positive control group (Tyr::CreERT2; BrafV600E mice), may not have been intensive enough to reveal subtle effects of STN1 deficiency on skin tumorigenesis." (PMID 40501869, 2025). "In contrast to the lack of a significant melanoma phenotype, our previous work demonstrated that STN1 deficiency promotes colorectal cancer (CRC) development in young adult mice, suggesting that the tumor-promoting effects of CST dysfunction may be tissue- and context-dependent." (PMID 40501869, 2025). "Thus, while our data suggest that STN1 depletion does not significantly alter melanoma formation in this model, the effects of CST deficiency on cancer development may be more pronounced in other tissues with different proliferative rates or exposure to distinct types of DNA damage." (PMID 40501869, 2025). "Our findings suggest that STN1 may not be a critical driver of UV-induced melanoma in adult mice." (PMID 40501869, 2025).
melanoma (continued). "While STN1 plays a critical role in maintaining genomic stability in both tissues, the absence of an observable effect in melanoma could be due to compensatory mechanisms that are more prominent in skin cells or the fact that melanocytes are less reliant on STN1 in the context of UV-induced damage." (PMID 40501869, 2025).
Coats plus syndrome (5 papers, 2019 to 2025). "Several studies have reported that biallelic pathogenic variants in CTC1 and STN1 are implicated in the development of Coats plus syndrome and, in rare instances, dyskeratosis congenita." (PMID 39198715, 2024). "Moreover, Coats plus syndrome, a pathology involving STN1 mutation, has been reported to affect fibroblast populations of the patient; fibroblasts were reported to be abnormally large and vacuolated, exhibiting proliferative arrest after a few divisions." (PMID 31248154, 2019). "Mutations in the telomere maintenance complex (the CST complex; CTC1, STN1, and TEN1) lead to cerebroretinal microangiopathy (Coats plus syndrome) with a failure of multiple organs." (PMID 34139671, 2021). "However, despite indications that loss of STN1 function leads to cellular senescence, no increase in SA-β-Gal staining (indicative of senescence) was reported for fibroblasts in the cases of Coats plus syndrome, and no pulmonary symptoms are mentioned in association with the pathology." (PMID 31248154, 2019).
colorectal cancer (5 papers, 2017 to 2025). A primary or metastatic malignant neoplasm that affects the colon or rectum. "We have investigated the role of CST in colorectal tumorigenesis and found that STN1 deficiency promotes colorectal cancer development in young adult mice via inhibiting base excision repair." (PMID 40501869, 2025). "Moreover, CST has been implicated in tumor development, as STN1 variants are associated with various types of cancer, and STN1 deficiency promotes colorectal cancer development in young adult mice." (PMID 38036565, 2023).
dyskeratosis congenita (5 papers, 2014 to 2025). Dyskeratosis congenita (DC) is a rare ectodermal dysplasia that often presents with the classic triad of nail dysplasia, skin pigmentary changes, and oral leukoplakia associated with a high risk of bone marrow failure (BMF) and cancer. "Mutations in human CTC1 and STN1 have mainly been associated with dyskeratosis congenita and Coats Plus (and references therein)." (PMID 40497960, 2025). "Concerning CST, mutations in human CTC1 and STN1 have been found to be mainly associated with dyskeratosis congenita and Coats Plus (and references therein), as well as several types of cancer." (PMID 40497960, 2025). "Mutations in CTC1 and STN1 are associated with two congenital genetic disorders, namely Coats plus (CP) syndrome (also known as cerebroretinal microangiopathy with calcifications and cysts) and dyskeratosis congenita (DKC)." (PMID 34283091, 2021). "Also, mutations in human CTC1, the ortholog of CDC13, are found in a number of diseases associated with telomere defects (Coats plus, dyskeratosis congenita and CRMCC); however, no equivalent mutations in STN1 or TEN1 have yet been identified in the same cohorts of patients." (PMID 24835988, 2014).
lung carcinoma (5 papers, 2016 to 2023). "Notably, we discovered a novel intron retention inside the 5′UTR of STN1 that is associated with the survival of lung cancer patients." (PMID 38067392, 2023).
colon cancer (3 papers, 2018 to 2025). "It is of note, however, that while our manuscript was in preparation, STN1 deficiency was reported to down-regulate DNA glycosylases and thus suppress base excision repair (BER), leading to an increased oxidative DNA damage and risk of colon cancer." (PMID 37590191, 2023). "Upon the disruption of STN1 expression using two independent small interfering RNAs (siRNAs), we observed a significant reduction in CTC1 levels in both telomerase‐positive HCT116 colon cancer cells and telomerase‐negative BJ fibroblasts." (PMID 40923710, 2025).
Coats disease (2 papers, 2022 to 2025). Coats disease (CD) is an idiopathic disorder characterized by retinal telangiectasia with deposition of intraretinal or subretinal exudates, potentially leading to retinal detachment and unilateral blindness. "Within the CST complex, mutations in CTC1 and STN1 have been established as contributors to ocular manifestations, such as exudative retinopathy and retinal telangiectasia, which have been frequently observed." (PMID 40215293, 2025). "Out of the 161 patients (175 eyes) that met the clinical criteria for Coats disease, 3 (two females and one male) with a bilateral involvement were excluded because brain MRI found calcifications in favor of CRMCC syndrome, which was confirmed by the presence of a mutation on genes CTC1 or STN1." (PMID 35991629, 2022).
cutaneous melanoma (2 papers, 2025). A primary melanoma arising from atypical melanocytes in the skin. "In addition, our analysis of the TCGA database revealed that CST genes, including STN1, are frequently downregulated in cutaneous melanoma tissues compared to normal tissues." (PMID 40501869, 2025). "While its role in maintaining genome stability is well-established, the specific contributions of STN1 to skin tumorigenesis remain poorly understood, and the potential link between STN1 dysfunction and cutaneous melanoma has not been explored." (PMID 40501869, 2025).
pulmonary fibrosis (2 papers, 2021). Chronic progressive interstitial lung disorder characterized by the replacement of the lung tissue by connective tissue, leading to progressive dyspnea, respiratory failure, or right heart failure. "Interestingly, they reported five shared genome segments with pulmonary fibrosis, FAM13A, DSP, and 17q21 already known, and two new segments, including loci near ZKSCAN1 and STN1 (formerly known as OBFC1)." (PMID 34502194, 2021).
skin cancer (2 papers, 2025). "We then generated a conditional knockout (cKO) mouse model with STN1 deficiency specifically in melanocytes to investigate its role in skin cancer formation." (PMID 40501869, 2025).
Infertility (1 paper, 2026). "Genetic deletion of stn1 leads to massive loss of oocytes prior to or during their development to stage IB, resulting in a male-like phenotype associated with infertility." (PMID 41998405, 2026).
osteosarcoma (1 paper, 2022). A usually aggressive malignant bone-forming mesenchymal neoplasm, predominantly affecting adolescents and young adults. "Using the TARGET‐osteosarcoma cohort, we found that patients with higher STN1 were associated with poorer OS and EFS." (PMID 36305631, 2022).
seizure disorder (1 paper, 2010). "In our cohort, only one subject had a seizure disorder (subject 1), although his 5 Mb deletion encompassed the entire NRXN1 gene as well as the genes for follicle-stimulating hormone receptor (FSHR), luteinizing hormone/choriogonadotropin receptor (LHCGR), and Stoned B-like factor (STN1)." (PMID 20468056, 2010).
telomere syndrome (1 paper, 2018). Accelerated aging syndromes often caused by inheritable gene mutations resulting in decreased telomere lengths. "CST is encoded by CTC1, STN1 and TEN1 in human cells and mutations in CTC1 and STN1 are associated with Coats plus disease, one of the heritable telomere syndromes." (PMID 30067734, 2018).
cancer (18 papers, 2015 to 2025). A tumor composed of atypical neoplastic, often pleomorphic cells that invade other tissues. "Cancer-associated STN1 variants impair STN1 phosphorylation, conferring inability of fork protection." (PMID 38036565, 2023). "Single nucleotide polymorphisms in CTC1 and STN1 are correlated with an increased risk of various cancers." (PMID 34283091, 2021). "In this study, we identify an intrinsically disordered region (IDR) in the OB domain of STN1 and analyze the functions of cancer-associated IDR variants and a number of alanine substitutions of individual polar or hydrophilic residues in this IDR." (PMID 34681076, 2021). "Furthermore, we observe that two cancer-associated missense mutations at or near S96 diminish STN1 phosphorylation." (PMID 38036565, 2023). "Cancer-associated STN1 mutations abolish STN1 phosphorylation, resulting in fork instability." (PMID 38036565, 2023). "The loss of S96 phosphorylation and increased NSD caused by the cancer-associated somatic mutations suggest that STN1 phosphorylation may play a role in the tumor development process." (PMID 38036565, 2023). "To date, the Cancer Genomics database lists four cancer-associated STN1 alterations, namely missense mutations E95G, S96V, V97A, and S102T, residing within this region, indicating that this IDR may be important for STN1 function." (PMID 34681076, 2021). "Specifically, the 5′ UTR intron regulates the translation efficiency of STN1, which is essential for cancer cell proliferation through maintaining telomere replication and genome stability." (PMID 38067392, 2023). "Collectively, our study uncovers that CaMKK2 and ATR-CHK1 target STN1 to enable its fork protective function, and suggests an important role of STN1 phosphorylation in cancer development." (PMID 38036565, 2023). "Supporting this, tumors with high a level of CTC1 and STN1 display low levels of telomerase activity, cancer stemness (an indicator of cancer progression), and genome instability." (PMID 35368664, 2022). "Cox regression revealed that CTC1, STN1, the CS score, and the CST score were associated with better survival in at least four cancer types, while TEN1 was associated with worse survival only in LGG." (PMID 35368664, 2022). "Some cancer types were found with both alterations of TEN1 amplification/CTC1 deletion (LIHC) or both of CTC1/STN1 deletions (PRAD) or all of the TEN1 amplifications and CTC1/STN1 deletions (BRCA and UCEC)." (PMID 35368664, 2022). "First, tumors have less CTC1/STN1 but more TEN1 expression than their adjacent normal tissues in a majority of cancer types." (PMID 35368664, 2022). "STN1 has also been identified as a mediator of chemotherapeutic resistance to DNA damaging agents; however, its suppression sensitizes cancer cells to these agents." (PMID 34395257, 2021). "Given that most cancer cells lines express high levels of telomerase, it is possible that reduced levels of Stn1 are inconsequential for the viability of cells in which telomere lengths can be maintained efficiently." (PMID 25684230, 2015). "These telomeric replication defects were also observed in human cancer cells subjected to shRNA-mediated Stn1 knockdown, although telomere lengths and cellular proliferation rates did not appear to be affected." (PMID 25684230, 2015). "It will be interesting to investigate whether impaired STN1 phosphorylation promotes tumor formation and whether it is possible to specifically target STN1 phosphorylation to facilitate cancer therapy." (PMID 38036565, 2023). "CS score was used since CTC1 and STN1 were co-expressed in most cancers." (PMID 35368664, 2022). "Collectively, these findings suggest that non-coding RNAs might be responsible for the suppression of CTC1 and STN1 in cancer." (PMID 35368664, 2022).
cancer (continued). "While chromosome abnormalities induced by STN1 depletion were fully rescued by expression of the RNAi-resistant WT-STN1, E95G or S96V failed to rescue, indicating that cancer-associated variants are deficient in maintaining genome stability." (PMID 34681076, 2021). "In addition to the effects of CST deletion or depletion on genome instability and cell growth, depletion of STN1 increased the sensitivity of cancer cells to various replication inhibitors that stall DNA polymerases." (PMID 34283091, 2021). "Changes in STN1 mRNA expression were also reported in a number of cancers." (PMID 30979824, 2019). "Knockdown of either Stn1 or Ctc1 in human cancer cells and in mouse fibroblasts results in substantially elongated telomeric G-overhangs, consistent with its recently demonstrated role in facilitating telomeric C-strand synthesis and negatively regulating telomerase." (PMID 25684230, 2015). "Interestingly, by mining the miRNA-target interaction database and analyzing the correlation between miRNA and CST expression, we found that CTC1 and STN1, but not TEN1, could be repressed by multiple miRNAs in various cancer types." (PMID 35368664, 2022).
tumor (7 papers, 2016 to 2025). "In the CRC model, STN1 depletion led to enhanced genomic instability, including increased replication stress and oxidative damage, which promoted tumor formation in the colon." (PMID 40501869, 2025). "Intriguingly, the retention level in the 5′UTR of STN1 was decreased in tumor samples compared with normal samples, and lower retention level is significantly associated with poorer survival outcomes in LUAD." (PMID 38067392, 2023). "Because the intron retention of the STN1 5′ UTR may downregulate STN1 protein level, knocking down STN1 should mimic the functional impact of increased IR levels, which is seen in adjacent normal tissues and in tumor tissues from patients with better prognosis." (PMID 38067392, 2023). "When comparing the expression of CST between tumor and paired adjacent normal samples, we found that CTC1 and STN1 were largely downregulated, whereas TEN1 was upregulated in tumors." (PMID 35368664, 2022). "This positive correlation data suggest that DNA methylation was not responsible for the downregulation of CTC1 and STN1 expression in tumor samples." (PMID 35368664, 2022). "Taken together, the identified IR event in the STN1 5’ UTR directly regulates STN1 protein production through uORF-mediated translation inhibition and nucleus detention, which in turn impacts tumor cell proliferation, clonogenicity and motility, ultimately influencing patient survival." (PMID 38067392, 2023). "Our work suggests that CTC1 and STN1, but not TEN1, are putative tumor suppressors." (PMID 35368664, 2022).
STN1 also shares sentences with these, for which no sentence is quoted: coronary artery disease (4 papers); lung adenocarcinoma (4); glioma (3); leukemia (3); uterine fibroids (3); cardiovascular disease (2); fibroids (2); ovarian carcinoma (2); thyroid cancer (2); basal cell carcinoma (1); benign tumors (1); brain tumors (1); breast carcinoma (1); chronic lymphocytic leukemia (1); colon adenocarcinoma (1); Combined immunodeficiencies (1); dementia (1); diffuse large B-cell lymphoma (1); endometriosis (1); ependymoma (1); glioblastoma (1); Hypertension (1); idiopathic interstitial pneumonia (1); lung squamous cell carcinoma (1); lymphocytic leukemia (1); lymphoid neoplasm (1); mesothelioma (1); neurodegenerative disease (1); nevus (1); non-Hodgkin lymphoma (1).
A further 13 diseases each share a sentence with STN1 in 1 paper.